IL6 (interleukin 6)
Diseases named in the same sentence as IL6 in open-access papers (continued):
Sharing a sentence is not in itself a finding about the gene and the disease.
diabetes (continued). "The effect of ARBs on IL-6 level reduction has been proposed in previous studies on patients with hypertension or diabetes and other conditions." (PMID 34285712, 2021). "There was a reduced level of inflammatory mediators, IL-6 and TNFα, in both diabetes and non-diabetes patients while using metformin." (PMID 34441802, 2021). "Next, we assessed the association between high levels of triglycerides, low levels of HDL-C and heart attack in those with diabetes in presence of pro-inflammatory markers (IL6, TNFα)." (PMID 33510184, 2021). "In several studies using markers like highly sensitive C-reactive protein (hsCRP), interleukin-6 (IL-6) and tumour necrosis factor alpha (TNFα), a link has been shown between chronic inflammation and development of cardiovascular disease and diabetes." (PMID 33997590, 2021). "A significant (p < 0.05) upregulation of hepatic TNF-α and IL-6 expression and downregulation (p < 0.05) of Nrf-2 expression were observed during diabetes onset." (PMID 34956587, 2021). "Higher levels of TNF-alpha, IL-1beta, and IL-6 were found in the serum of type 2 diabetes mellitus compared with healthy control, which correlate with the development and progression of DR." (PMID 34699316, 2021). "Changes in diabetes-related inflammatory status were measured in terms of IL-6, TNF-α, and IL-1β levels in the serum and phospho NFκB-p65 protein expression." (PMID 34439476, 2021). "SGLT2 inhibitors reduce nuclear factor kappa B (NF-κB), interleukin-6 (IL-6), monocyte chemoattractant protein-1 (MCP-1), and other inflammatory factors implicated in DKD pathogenesis in experimental models of diabetes and in T2DM patients." (PMID 34297135, 2021). "Individuals with diabetes have also been shown to elevate levels of the proinflammatory cytokine, especially IL-1, IL-6, and tumor necrosis factor-alpha (TNF-alpha), and different markerssuch as C reactive protein, D-dimer, and fibrinogen." (PMID 35540698, 2021). "In the adjusted model, hepcidin, log of IL-6, age, NSAID consumption and diabetes were conditions associated with CKD anemia (p < 0.05)." (PMID 34836070, 2021). "One study evaluated the proinflammatory cytokine levels (TNF-α, IL-6) in left ventricular diastolic dysfunction (LVDD), the earliest manifestation of diabetes-induced left ventricular dysfunction, and the result was increased plasma levels of IL-6 and TNF-α." (PMID 34506248, 2021). "Peripheral delivery of recombinant irisin protein via intraperitoneal injection was sufficient to reduce levels of pro-neuroinflammatory markers GFAP, interleukin-1β (IL-1β) and interleukin-6 (IL-6) in the CNS of a streptozotocin-induced diabetic mouse model." (PMID 34276532, 2021). "AA, the precursor of LXA4 and PGE2, prevented streptozotocin (STZ)-induced type 1 and type 2 diabetes mellitus and suppressed plasma IL-6 and TNF-α levels and the pro-inflammatory gene NF-κB to the same extent as that of LXA4." (PMID 34944517, 2021). "Diabetes mellitus is associated with high levels of cytokines TNF-α, IL-6, IL-1β, and decreased interferon-γ." (PMID 34926852, 2021). "Induction of diabetes resulted in a significant (p < 0.05) increase in plasma and hepatic IL-6 (645.3 and 104.5%, respectively) and TNF-α (69.4 and 479.8%, respectively) concentrations when compared with normal rats." (PMID 34956587, 2021). "It is known that diabetes, high body mass index, high glycated hemoglobin and raised serum IL-6 levels are predictive of poor outcomes in coronavirus disease 2019 (COVID-19)." (PMID 33530554, 2021). "The presence of a chronic subclinical proinflammatory state has been well-described in the setting of diabetes mellitus as activation of IL-1β, TNF-α, and IL-6 signaling pathways often precedes the onset of diabetes mellitus." (PMID 33755703, 2021). "In a diabetes animal model, the proinflammatory cytokines IL-6, TNF-α, and IL-1β increased significantly in rat pancreatic tissue." (PMID 33774704, 2021).
diabetes (continued). "Patients with elevated IL-6 (Group 2) were more likely to present with diabetes mellitus (64.3% vs. 41.7%; p = 0.046) and hypercholesterolemia (76.2% vs. 58.2% p = 0.03)." (PMID 33535417, 2021). "IL-6 is a powerful predictor of the development of diabetes complications such as diabetic nephropathy." (PMID 34926852, 2021). "On the other hand, obesity as a general comorbidity with diabetes, improves the systemic chronic inflammation by affecting the both innate and adaptive immune systems as well as the level of IL-6 and even TNF-α." (PMID 33746897, 2021). "On the other hand, it has been proved that the increased cytokine production by Th1 (IFN-γ, IL-2, TNF-α, and TNF-β) and Th17 (IL-6, IL-17A, and IL-17F) in diabetics can affect the HbA1c level." (PMID 33746897, 2021). "The odds for heart attack among those with diabetes, increased by 20 fold in presence of high levels of triglycerides, TNFα, and IL6 when coupled with low levels of high-density lipid cholesterol (HDL-C)." (PMID 33510184, 2021). "In the absence of studies on the effects of different exercise patterns on TNF-α and IL-6 in diabetes, rigorous conclusions cannot be drawn on the effects of different exercise patterns." (PMID 33456672, 2020). "Induction of diabetes and/or AFB1 intoxication in the 3rd, 5th, and 7th groups was associated with significantly elevated serum 8-OhdG, IL-1β, IL6, and TNF-α levels, compared to the control group." (PMID 32104544, 2020). "A large sample study showed that the risk of cardiovascular disease, pneumonia, diabetes, and lung cancer increased by 2–4 folds with a systemic inflammation measured by six inflammatory markers (CRP, IL-6, CXCL8, fibrinogen, TNF-α, and leukocytes)." (PMID 32280354, 2020). "It is evident that monocytes isolated from obese humans with diabetes display an inflammatory phenotype and secrete higher levels of pro-inflammatory mediators such as IL-6, MCP-1, and IL-1β leading in metabolic dysfunction." (PMID 33033337, 2020). "Conversely, diabetes, high blood sugar, high glycemic load foods, starchy foods, and potentially coffee can actually increase IL-6 levels." (PMID 32302283, 2020). "Permanent hyperglycemia in diabetes condition leads to increase expression of inflammatory markers like IL-6 and TNF-α as observed in this study." (PMID 33293987, 2020). "The close pathological and physiological tie between COPD and metabolic diseases is also revealed in the fact that such systemic inflammation markers as CRP, TNF-a and IL-6 would increase in diabetes and play an important role in the development of diseases." (PMID 33108241, 2020). "The present study is the first to show the beneficial effects of long-term inhibition of the renal NF-κB system in experimental diabetes, with consequent reduction of the production of IL-6, one of its main targets." (PMID 32116790, 2020). "After adjustments for age, C-reactive protein, interleukin-6, procalcitonin, diabetes and hypertension, the highest tertile remained statistically significant, and the relative risk was OR 7.8, 95% CI 2.3–26.4." (PMID 32641174, 2020). "IL-6 promotes leukocyte adhesion, microvascular leakage, and TNF-α product in microglial cells in diabetes as these pathological phenotypes were dramatically reduced in the IL-6 knockout mice with diabetes." (PMID 33013692, 2020). "Patients with low testosterone have elevated IL-6 levels, higher incidences of diabetes, high rates of obesity, and higher overall mortality." (PMID 32302283, 2020). "In our results, positive correlations of Firmicutes with pro-inflammatory IL-1β, TNF-α, IL-6, IL-17A and LPS demonstrated that both pro-inflammatory indicators and Firmicutes contributed to pathogenesis of diabetes." (PMID 32028957, 2020). "Diabetes-mediated inflammation and hyperglycemia activate RORγt, wherein hyperglycemia-driven IL-6 and glucose sensitive stimulatory factors co-activate a STAT3 signaling cascade that activates RORγt." (PMID 32429598, 2020).
diabetes (continued). "It has been well documented that the appearance of peripheral neuropathy in type 1 and type 2 diabetes mellitus is strongly associated with increases in inflammatory biomarkers, including C-reactive protein, TNF-α, and IL-6." (PMID 32973438, 2020). "In our study, we found that increased Blautia was positively correlated with inflammatory indicators (IL-1β, TNF-α, IL-6 and LPS) in diabetes." (PMID 32028957, 2020). "Third, there are few studies on the effects of different types of exercise on TNF-α and IL-6 in diabetes, making it impossible to draw a rigorous conclusion on the effects of different types of exercise." (PMID 33456672, 2020). "Fucoidan isolated from Saccharina japonica diminished the toxic effects of diabetes and/or aflatoxin B1 on the liver and kidneys via reducing the blood glucose levels and serum levels of IL-1β, IL-6, and TNF-α." (PMID 33066186, 2020). "IL-6 has important roles in inflammation, autoimmunity, injury, hematopoiesis, diabetes, atherosclerosis, rheumatoid arthritis, and cancer." (PMID 32708317, 2020). "Previous investigations have shown that in diabetes mellitus the production of inflammatory cytokines including IL-1, IL-6 and TNF-α increase." (PMID 32817750, 2020). "AdipoRon decreased diabetes-induced transcription of proinflammatory cytokines, such as IL-6, MCP-1, and TNFα in the kidney of db/db mice." (PMID 32832003, 2020). "Proinflammatory cytokine serum IL-6 concentrations showed a higher trend in acromegaly patients with diabetes than controls (p = 0.051)." (PMID 33154456, 2020). "Increases in age, diabetes, hypertension, cardiovascular disease comorbidities, interleukin-6 (IL-6), procalcitonin, and D-dimers, as well as decreases in lymphocytes were all risk factors for the disease." (PMID 33232275, 2020). "In our study, however, patients with diabetes shared similar lymphocyte and neutrophil counts than patients without diabetes, the inflammation-related biomarkers (e.g., IL-6)." (PMID 32760350, 2020). "- Diabetes resistance in LjN6.2-fed BBDP rodents was correlated to a Th17 cell bias within the mesenteric lymph nodes - Cytokines IL-6 and IL-23, respectively, were significantly higher within the mesenteric lymph nodes of LjN6.2-fed BBDP." (PMID 33072796, 2020). "VEGF-A is activated by advanced glycation end products via ERK1/2, P38, and STAT3 in patients with diabetes and the elderly through upregulation of osteocyte-derived IL-6 and secretion, and osteocyte apoptosis." (PMID 32708317, 2020). "IL-6 promotes the production by T cells and macrophages of CRP associated with increased risk of diabetes, hypertension, and cardiovascular disease." (PMID 32023901, 2020). "The C3 knockout in the present study also caused a decrease in the expression of inflammatory factors, such as IL‐6 and TNF‐α, thereby reducing inflammation caused by diabetes." (PMID 32794619, 2020). "Elevated circulating IL-6 level is concerned with several complications, including ischemic heart disease, diabetes, and osteoporosis." (PMID 32280354, 2020). "Other corroborating evidences are the increased inflammatory markers (NF-κB, TNFα, IL-6, and IL-10) reported in cortical tissues of murine diabetes models, HK2 cell cultures under high glucose environment (NF-κB), and cortical portions of T2D patients (NF-κB)." (PMID 32377524, 2020). "Patients with diabetes are often accompanied by chronic metabolic inflammation, IL-1β, IL-6 and TNF-α and other inflammatory cytokines are upregulated." (PMID 32722636, 2020). "Interleukin-6 (IL-6), fibrinogen and C-reactive protein were reported significantly more elevated in the patients with diabetes and COVID-19 infection." (PMID 32438687, 2020). "It is reported that the large blood glucose fluctuation not only increases tumor necrosis factor-α, interleukin-6, and platelet aggregability, but also decreases endothelium dependent vasodilation even before the onset of diabetes." (PMID 32927895, 2020).
diabetes (continued). "Studies focusing in diabetes found that patients with type 2 diabetes had a marked elevation of circulating IL-8 and IL-6 levels." (PMID 33166358, 2020). "The level of IL-6 in urine can reflect the degree of glomerular and tubulointerstitial lesions, which has guiding significance for the diagnosis of diabetes mellitus." (PMID 32215271, 2020). "In diabetes mouse muscle, protein carbonyl (PC) level was significantly higher, but IL-6 and Glut-4 level were significantly lower than normal." (PMID 31327904, 2019). "IL-6 is implicated in autoimmune and immunoinflammatory diseases such as SLE, rheumatoid arthritis, diabetes and cancer." (PMID 31137755, 2019). "The higher level of muscle IL-6 was found at lower muscle PC level of diabetes-treated golden sea cucumber extract." (PMID 31327904, 2019). "Diabetes significantly enhanced the level of IL-6 in comparison to that in the control (p < 0.05), while LPS treatment (1 μg/ml, 24 h) increased IL-6 only in the control cultures." (PMID 31197747, 2019). "Strikingly, other studies have shown that Il-6 can possibly have an anti-inflammatory role in diabetes, confirming that the molecular signalization in diabetes is quite complex." (PMID 31225503, 2019). "Diabetes is known to alter IL-6 expression as elevated serum IL-6 is reported in both type I and type II diabetes patients." (PMID 31073533, 2019). "A total of 104 (60%) patients with CAC > 100 AUs were older, had higher prevalence of both clinical CVD and diabetes, higher level of high sensitivity C-reactive protein, tumour necrosis factor, interleukin-6 and lower T-score of tBMD." (PMID 30777028, 2019). "IL-6 was secreted higher as muscle responded to acute inflammation, but it was impaired as responded to chronic inflammation, such as in diabetes mellitus." (PMID 31327904, 2019). "This seems to indicate that the regulation of IL-6 and IL-6Rα by hyperglycemia/diabetes resides at the posttranscriptional level." (PMID 31073533, 2019). "The results of the findings indicate that diabetes mediates testicular damage by increasing the expression of NF-κB which elicit inflammatory cytokine activities, such as those of IL-6, TNF-α, and IL-1β, to promote inflammatory responses." (PMID 31583254, 2019). "Increased basal levels in IL-6, IL-1Ra, or MCP-1 are associated with coronary heart disease (CHD), which is a macrovascular complication of diabetes." (PMID 29924291, 2019). "IL-6 is a multifunctional cytokine that plays an important role in inflammation and autoimmune disorders including diabetes, atherosclerosis, rheumatoid arthritis, systemic lupus erythematosus, or psoriasis." (PMID 31438590, 2019). "Other studies have shown that pro-inflammatory cytokines (e.g., IL-6 and TNF-α) are involved in brain dysfunction caused by diabetes." (PMID 31197747, 2019). "Present study showed that pro-inflammatory markers i.e., TNF-α, IL-1β, and IL-6 together induce chronic inflammation condition to promote CAD in diabetes." (PMID 30674322, 2019). "There are particular factors affecting the IL-6 level in CAD patients, such as co-occurrence of risk factors and condition of patients, age, smoking, diabetes, hypertension, dyslipidemia, body mass index, and inflammation." (PMID 31739518, 2019). "Even so, most research concerning IL-6 and diabetes has focused on the role of IL-6 during the development and progression of diabetes." (PMID 31073533, 2019). "This study uncovered the novel role of the IL-6/STAT3 pathway in diabetes-induced circulating immune cell activation, and the development of diabetic retinal vasculopathy." (PMID 31286987, 2019). "Furthermore, IL-6 has been found to be associated with vascular dysfunction and the promotion of angiogenesis, which suggest IL-6 may be a promising new therapeutic target to prevent diabetes-induced vascular damage." (PMID 32116675, 2019). "IL‐6 is adversely involved in diabetes progression, and we found evidence of sex differences in IL‐6 stress responses." (PMID 30666661, 2019).
diabetes (continued). "We found a significant improvement of muscle IL-6 protein level in diabetes-treated group compared to diabetes group (p=0.008)." (PMID 31327904, 2019). "In this study, treated mice had higher circulating levels of IL-6, a cytokine commonly found to be positively correlated with diabetes and obesity." (PMID 30728429, 2019). "Unlike what happened when treating diabetic rats with ADA, ADORA3 antagonism does not significantly affect the levels of IL-10, while only attenuates the levels of IL-6 found in diabetes." (PMID 31540220, 2019). "The potential role of IL-15 and IL-6 in the pathogenesis of diabetes is still discursive, and only a handful of reports concerning their role in LADA are available." (PMID 31772933, 2019). "As an example, CHOP was shown to be involved in the release of IL-6 in macrophages during atherosclerosis and generation of reactive oxygen species (ROS) and ROS-induced damage in diabetes." (PMID 30174670, 2018). "In the ECLIPSE cohort, most COPD patients with heart disease had elevated IL-6, IL-8, and fibrinogen, while those with hypertension had elevated fibrinogen and those with diabetes had elevated CRP." (PMID 29720140, 2018). "During the co-occurrence of opisthorchiasis and diabetes, Il-6, Il-12 and Il-13 were dominantly increased." (PMID 29953446, 2018). "A vitro experiment has shown that ginsenoside Re can improve the expression of endothelial cell function markers such as endothelin, nitric oxide, vascular endothelial growth factor and interleukin-6 (IL-6) during the early stage of diabetes." (PMID 29765322, 2018). "Our results revealed that HSP60 levels were attenuated in lean subjects with diabetes along with increased expression of the inflammatory markers IL-6 and TNF-α, as observed in our obese subjects." (PMID 29467719, 2018). "Increases in inflammatory cytokines in diabetes promote tumour development, which include interleukin-6 (IL-6), monocyte chemoattractant protein, plasminogen activator inhibitor-1 (PAI-1), adiponectin, leptin, and tumor necrosis factor-alpha." (PMID 30271790, 2018). "Induction of diabetes in rats using streptozotocin increased retinal IL-6 and TNFα, whereas anti-inflammatory IL-10 was decreased, suggesting a pro-inflammatory and neurotoxic shift." (PMID 29301251, 2018). "Enhanced expression of AGEs in diabetes not only provokes NF-κB activation, but also leads to an subsequent increase in IL-6 and TNF-α release, which further exacerbates bone resorption." (PMID 30459613, 2018). "Several studies have demonstrated that initial elevated levels circulating IL-6, plasminogen activator inhibitor-1 (PAI-1), C-reactive protein (CRP) and fibrinogen, are associated with the manifestation of diabetes." (PMID 30443223, 2018). "The results of the present study noted an insignificant difference in IL-6 levels among patients afflicted with both diabetes and periodontitis (group 2) and those patients who suffered only from chronic periodontitis (group 3)." (PMID 30186882, 2018). "To assess the effect of allicin on the levels of proinflammatory cytokines, we analyzed the expression of IL-1β and IL-6 in plasma and kidney using rats with one month of diabetes evolution and another month under treatment with allicin." (PMID 30314265, 2018). "Similar observation of comparable salivary IL-6 levels between systemically healthy and diabetes individuals with healthy periodontium has been reported by others." (PMID 29487749, 2018). "We recently developed conditions for culturing podocytes which mimic those experienced by podocytes during diabetes, an environment rich in glucose, insulin and inflammatory cytokines, TNFα and IL-6, which promotes insulin resistance." (PMID 29500363, 2018). "Inflammatory biomarkers, such as white cell counts (WBC), C-reactive protein (CRP), tumor necrosis factor-α (TNF-α), and interleukin-6 (IL-6), were showed to be correlated with prevalent and incident diabetes." (PMID 29651306, 2018).